USP12 (ubiquitin specific peptidase 12)
Description:
Deubiquitinating enzyme that plays various roles in the regulation of the immune response and inflammation. During TCR engagement and activation, translocates into the cytoplasm and deubiquitinates its substrates LAT and TRAT1 and prevents their lysosome-dependent degradation to stabilize the TCR signaling complex at the plasma membrane. Plays an essential role in the selective LPS-induced macrophage response through the activation of NF-kappa-B pathway. In addition, promotes that antiviral immune response through targeting DNA sensor IFI16 to inhibit its proteasome-dependent degradation. Participates in the interferon signaling pathway and antiviral response independently of its deubiquitinase activity by maintaining nuclear phosphorylated STAT1 levels via inhibition of its CREBBP-mediated acetylation and subsequent dephosphorylation. Plays an intrinsic role in promoting the differentiation, activation and proliferation of CD4(+) T-cell by activating the NF-kappa-B signaling pathway through deubiquitinating and stabilizing B-cell lymphoma/leukemia 10/BCL10 (By similarity). In myeloid-derived suppressor cells promotes the activation of the NF-kappa-B via deubiquitination and stabilization of RELA (By similarity). Regulates the 'Lys-63'-linked polyubiquitin chains of BAX and thereby modulates the mitochondrial apoptotic process. Negative regulator of NOTCH signaling that specifically deubiquitinates non-activated NOTCH receptors to target them for lysosomal degradation; deubiquitination of NOTCH stimulates its transport form late endosomes to lysosomes. Protects neurons against HTT/huntingtin-induced polyglutamine expansion-dependent neurodegeneration through regulation of autophagic flux. This function is independent of deubiquitinase activity or of other components of the USP12-WDR20-WDR48 deubiquitinating complex (By similarity). In complex with WDR48, acts as a potential tumor suppressor by positively regulating PHLPP1 stability. (Microbial infection) Forms a complex with Epstein-Barr virus protein EBNA3 which is an active deubiquitinase activity that may select specific substrates to promote B-lymphocyte transformation.
Synonyms: UBH1; USP12L1
Tractability: Small molecule: a structure with a bound ligand is known. Antibody: UniProt places it where antibodies can reach, with high confidence; its Gene Ontology location is reachable by antibodies, with high confidence. PROTAC: ubiquitination databases record sites on it.
Target class: Enzyme; Hydrolase
Gene: Protein-coding gene on chromosome 13 (27,066,150 to 27,171,885, reverse strand). Ensembl gene ENSG00000152484.
Subcellular location: Nucleus; Cytoplasm; Cell membrane
Subcellular location (Human Protein Atlas): Nucleoplasm
Pathways (Reactome):
Metabolism of proteins: Ub-specific processing proteases
Gene Ontology:
Molecular function: cysteine-type deubiquitinase activity; cysteine-type endopeptidase activity; protein binding; deubiquitinase activity
Biological process: protein deubiquitination
Cellular component: cytoplasm; nucleus; peptidase complex; plasma membrane; nucleoplasm
Genetic constraint (gnomAD): Loss-of-function variants: 16 observed, 40.47 expected, observed/expected ratio (o/e) 0.4, 90% interval 0.27 to 0.6. The upper end of that interval is the gene's LOEUF score, 0.6, which puts it in group 2 of 6, group 1 being the genes least tolerant of losing a copy. Missense variants: 240 observed, 440.86 expected, observed/expected ratio (o/e) 0.54, 90% interval 0.49 to 0.61. Synonymous variants: 148 observed, 148.48 expected, observed/expected ratio (o/e) 1, 90% interval 0.87 to 1.14.
Homologues: Orthologues: macaque USP12 (100% identical), pig USP12 (99% identical), mouse Usp12 (98% identical), rabbit USP12 (96% identical), guinea pig USP12 (96% identical), tropical clawed frog usp12 (95% identical), dog USP12 (95% identical), rat Usp12 (95% identical), rat Usp12l1 (95% identical), zebrafish usp12a (92% identical), zebrafish usp12b (91% identical), Drosophila melanogaster Usp12-46 (71% identical), and 1 more. Paralogues in human: USP46 (88% identical), USP39 (24% identical).
Diseases named in the same sentence as USP12 in open-access papers:
USP12 is named in the same sentence as 31 diseases in open-access papers, as found by Europe PMC text mining. Sharing a sentence is not in itself a finding about the gene and the disease. The quoted sentences say what the papers report.
prostate carcinoma (9 papers, 2014 to 2024). A carcinoma that arises from epithelial cells of the prostate gland. "The mechanisms underlying the influence of USP12 on apoptosis have also been researched in some other diseases, such as cardiac hypertrophy, prostate cancer, and hepatocellular carcinoma." (PMID 37752518, 2023). "According to a recent study, USP12 plays a critical role in prostate cancer through deubiquitination of androgen receptors to increase Ak strain transforming (AKT) signaling." (PMID 39664521, 2024). "USP12 also regulates pAkt in prostate cancer cell lines and stabilizes two Akt phosphatases (PHLPP and PHLPPL)." (PMID 36361894, 2022). "An earlier study suggested that USP12 deubiquitinates the androgen receptor to promote the AKT signaling pathway in prostate cancer." (PMID 33941870, 2021). "We found that depleting Usp12 protein resulted in the sensitisation of prostate cancer cells to Akt inhibition irrespectively of their androgen sensitivity and AR status." (PMID 25216524, 2014). "This study also provides updated information on the roles and functions of USP12 in different types of cancers and other diseases, including prostate cancer, breast cancer, lung cancer, liver cancer, cardiac hypertrophy, multiple myeloma, and Huntington's disease." (PMID 37752518, 2023). "We propose that Usp12 inhibition could offer a therapeutic alternative for castration resistant prostate cancer." (PMID 25216524, 2014). "USP12, a DUB of the ubiquitin-specific protease (USP) family, has been reported to play a critical role in prostate cancer, HeLa, macrophage, and neuronal cells." (PMID 33941870, 2021). "Relationships between transcription factors and DUBs can be complex: for example USP7, USP12, USP14, USP22 all appear to regulate the stability and function of androgen receptor (AR) in prostate cancer." (PMID 30854565, 2019). "To validate the shared role of USP12 and USP46 in prostate cancer cell biology we individually silenced both genes in PC cells and performed full transcriptome analysis to establish the extent of their shared functions." (PMID 29861848, 2018). "In this study we have investigated the relationship between Usp12, PHLPP and PHLPPL tumour suppressors in the regulation of AR transcriptional activity in prostate cancer (PC)." (PMID 25216524, 2014). "To assess if Usp12 additionally controls AR phosphorylation and activity by regulating pAkt levels, we overexpressed AR and Usp12 in the PC3 prostate cancer cell line and assessed the phosphorylation status of the receptor." (PMID 25216524, 2014). "On the other hand, USP12 promoted prostate cancer (PC) cells proliferation by forming a complex with Uaf-1 and WDR20 and deubiquitinating AR, thereby increasing AR stability and transcriptional activity, whereas USP12 silencing led to a significant decrease in PC cell proliferation." (PMID 37752518, 2023). "Galeterone was reported to be able to inhibit USP12 and USP46 enzymatic activity to control prostate cancer growth and survival, which is not surprising considering their high degree of homology and functional overlap." (PMID 37752518, 2023).
Huntington disease (7 papers, 2018 to 2023). Huntington disease (HD) is a rare neurodegenerative disorder of the central nervous system characterized by unwanted choreatic movements, behavioral and psychiatric disturbances and dementia. "Also, USP12 causes autophagy and confer neuroprotection in Huntington’s disease (HD)." (PMID 33498168, 2021). "In Huntington's disease (HD), USP12 was identified as a potent inducer of neuronal autophagy due to its interaction with HD mutant protein (mHTT)." (PMID 37752518, 2023). "One study reported that USP12 modifies mHTT-mediated neurodegeneration and toxicity in neurons obtained from rodents and patients with Huntington’s disease." (PMID 36361894, 2022).
breast carcinoma (5 papers, 2021 to 2025). "Overexpression of MDK rescued the loss of angiogenesis ability mediated by knockdown of USP12 in breast cancer cells in vitro and in vivo." (PMID 34759262, 2021). "The deubiquitinase ubiquitin-specific protease 12 (USP12) can promote angiogenesis in breast cancers by stabilizing MDK and promoting the downstream activation of the AKT pathway and VEGF receptor 3 (VEGFR3)." (PMID 40429950, 2025). "We further verify that USP12 induces breast cancer angiogenesis through MDK by using the mouse aortic ring assay." (PMID 34759262, 2021). "KM survival analysis showed that the DMFS of breast cancer patients with high USP12 levels was significantly worse than that of patients with low USP12 levels." (PMID 34759262, 2021). "Then, we further verified these DUBs in the orthotopic mouse lung metastasis model and identified that ubiquitin-specific protease 12 (USP12) is responsible for breast cancer metastasis." (PMID 34759262, 2021). "Here, we checked the level of Phospho-Akt in breast cancer MDA-MB-231 cells after knocking down USP12, and we found that knocking down of USP12 can reduce the Phospho-Akt (Ser473) level." (PMID 34759262, 2021). "In an orthotopic breast cancer model, silencing USP12—an MDK stabilizing protein—reduced lung metastases in a manner that could be reversed through MDK supplementation." (PMID 40429950, 2025). "Interestingly, however, increased levels of USP12 and USP46 have been associated with the progressions of several cancers, including breast cancer, liver cancer, and multiple myeloma." (PMID 39506038, 2024). "We revealed that the DMFS of breast cancer patients with high USP12 was worse than that of others." (PMID 34759262, 2021). "Moreover, the USP12 level was positively correlated with the MDK level in breast cancer tissue samples." (PMID 34759262, 2021). "MDK gene was knocked down at the same time in breast cancer cells overexpressing USP12." (PMID 34759262, 2021). "Collectively, these results indicate that USP12 could promote angiogenesis in breast cancer through upregulating MDK." (PMID 34759262, 2021). "Furthermore, our data revealed that USP12 promoted breast cancer metastasis by upregulating MDK protein levels." (PMID 34759262, 2021). "To assess whether USP12 promotes breast cancer angiogenesis by upregulating MDK, we overexpressed MDK in MDA-MB-231 and MCF7 cells with USP12 knockdown and measured angiogenesis by HUVEC migration and tube formation assays in vitro." (PMID 34759262, 2021). "In this study, through screening a series of DUBs related to breast cancer distant metastasis-free survival (DMFS) in the Kaplan-Meier Plotter database, we identified ubiquitin-specific protease 12 (USP12) as a key deubiquitinating enzyme for breast cancer metastasis." (PMID 34759262, 2021). "Therefore, USP12 was identified as a key molecule responsible for breast cancer metastasis." (PMID 34759262, 2021). "Furthermore, our results showed that the supernatant from USP12-overexpressing breast cancer cells could promote angiogenesis according to human umbilical vein endothelial cell (HUVEC) migration and tube formation assays." (PMID 34759262, 2021). "Therefore, the USP12–MDK axis could serve as a potential target for the therapeutic treatment of breast cancer metastasis." (PMID 34759262, 2021). "Thus, the USP12-MDK axis may be a potential target for breast cancer metastasis treatment." (PMID 37752518, 2023). "Our data revealed that USP12 and MDK were both highly expressed in breast cancer tissues compared with adjacent tissues." (PMID 34759262, 2021). "To further validate the clinical significance of USP12 and MDK in breast cancer metastasis, we detected their expression levels in breast cancer clinical tissue specimens." (PMID 34759262, 2021).
breast carcinoma (continued). "Consistent with USP12, high MDK expression also predicted a poor prognosis in breast cancer patients." (PMID 34759262, 2021). "There was a strong positive relationship between USP12 and MDK protein expression in clinical breast cancer samples." (PMID 34759262, 2021). "Consistent with the pattern for USP12, high MDK expression predicted lower DMFS and overall survival (OS) in breast cancer." (PMID 34759262, 2021). "To validate the results of our screens, we used Crispr/Cas9 technology to knockout (KO) the USP12, USP46, WDR20, and WDR48 genes either individually or in combination in at least two different mouse fibroblast and human breast cancer MDA-MB-231 cell clones, respectively." (PMID 39506038, 2024). "USP12 can also activate the Akt signaling pathway in tumors and endothelial cells by upregulating MDK, and promoting VEGFR3 expression through the mTOR signaling pathway, which then promotes the occurrence and progression of breast cancer." (PMID 37752518, 2023). "Moreover, the knockdown of USP12 reduces the ability of lung metastasis and CD31 (vascular endothelial cell marker) protein levels in mice with breast cancer." (PMID 37752518, 2023). "Indeed, a recent study reported that USP12 deubiquitinates and stabilizes MDK and this stabilization promotes breast cancer angiogenesis." (PMID 35487917, 2022). "In this study, through screening DUBs related to breast cancer DMFS in the KM Plotter database and confirming the results with the in vivo metastasis mouse model, we identified that USP12 could be a chief contributor to breast cancer metastasis." (PMID 34759262, 2021). "Collectively, our study revealed that USP12 is responsible for deubiquitinating and stabilizing MDK, which induces breast cancer metastasis by promoting angiogenesis, and provides a novel regulatory mechanism for breast cancer metastasis." (PMID 34759262, 2021). "Moreover, coordinated upregulation of USP12 and MDK was demonstrated in clinical breast cancer samples." (PMID 34759262, 2021). "Also, high USP12 and MDK expression predicts poor prognosis in breast cancer patients." (PMID 37752518, 2023).
hepatocellular carcinoma (3 papers, 2021 to 2023). A malignant tumor that arises from hepatocytes. "Knockdown of USP12 (Ubiquitin-specific protease 12) has been reported to inhibit proliferation of hepatocellular carcinoma cell lines via p38/MAPK pathway." (PMID 36077645, 2022). "USP12 is a potential target for the treatment of Hepatocellular Carcinoma (HCC), which can prevent G2/M and trigger apoptosis." (PMID 33498168, 2021). "USP12 has been researched in hepatocellular carcinoma to some extent." (PMID 37752518, 2023). "Similarly, the positive or negative effect of USP12 on cell proliferation was also found in HPV-negative human cervical cancer, hepatocellular carcinoma (HCC), non-small cell lung cancer (NSCLC), and multiple myeloma (MM)." (PMID 37752518, 2023).
lung carcinoma (3 papers, 2014 to 2023). "All these findings indicate the great potential of USP12 to be a therapeutic target in lung cancer and deserve more research to explore novel effective therapies." (PMID 37752518, 2023). "Small hairpin RNA-mediated silencing of USP12 confirmed the findings in both human and mouse lung cancer cells, as evidenced by ELISA quantification." (PMID 34381028, 2021). "Here the authors show that deubiquitinase USP12 downregulation contributes to development of an immune-suppressive tumour microenvironment in KRAS-driven lung cancers and mechanistically this is through the insufficient deubiquitination of the NF-κB inhibitor, PPM1B." (PMID 34381028, 2021). "Taken together, these results suggest that USP12 in lung cancer cells may function to regulate the tumour response to anti-PD-1 therapy." (PMID 34381028, 2021). "Interestingly, inhibition of Usp1, a close homologue of Usp12 has been shown to have promising results in lung cancer systems which was achieved by inhibiting the Usp1-Uaf-1 complex." (PMID 25216524, 2014). "We also examined whether a mutual regulation occurred between USP12 and AKT, and the results showed that USP12 overexpression did not significantly affect AKT phosphorylation in human lung cancer cells." (PMID 34381028, 2021).
multiple myeloma (3 papers, 2022 to 2024). "Previous studies show that USP12 promotes the growth of multiple myeloma (MM) cells and USP12 knockdown significantly inhibits cell proliferation." (PMID 37752518, 2023). "In the context of autophagy, the study of multiple myeloma (MM) showed that USP12 could interact with the key autophagy mediator HMGB1 (high mobility group box-1) protein to deubiquitinate and stabilize it." (PMID 37752518, 2023). "Recently, it was reported that USP12, another USP family member, is highly expressed in multiple myeloma cells and binds to HMGB1 to deubiquitinate and stabilize HMGB1, resulting in the promotion of pro-survival autophagy in myeloma." (PMID 36585612, 2022).
non-small cell lung carcinoma (3 papers, 2021 to 2024). A group of at least three distinct histological types of lung cancer, including non-small cell squamous cell carcinoma, adenocarcinoma, and large cell carcinoma. "Here, we show that USP12 expression is downregulated in KrasG12D-driven mouse lung tumour and human non-small cell lung cancer (NSCLC)." (PMID 34381028, 2021). "Here, we show that the deubiquitinase USP12 is commonly downregulated in the KrasG12D-driven mouse lung tumour and human non-small cell lung cancer owing to the activation of AKT-mTOR signalling." (PMID 34381028, 2021). "For example, USP12 could deubiquitinate RRM2 and promote non-small cell lung cancer progression." (PMID 38605077, 2024).